IL4 (interleukin 4)
Diseases named in the same sentence as IL4 in open-access papers (continued):
Sharing a sentence is not in itself a finding about the gene and the disease.
tumor (continued). "Our in vitro data also showed that tumor Sdc-1 silencing did not significantly alter the proportion of the Th2 (IL4+CD4+) subset among CD4+ T cells of non-IBC patients under indirect and direct co-culture conditions." (PMID 31145753, 2019). "To address the question whether in vivo M(LPS±) or in vitro classically/alternatively activated (IL-4) gene signatures can predict cancer survival, we used the PRECOG database that ranks genes by overall tumor survival." (PMID 31178859, 2019). "Interestingly, the injection of CD8+ cultured in Th9 skewing conditions (IL-4, TGF-β, and anti-IFNγ) was shown to give rise to Tc9 with stronger anti-tumor tumor effects than IFN-γ cytolytic CD8+ T cells in pre-clinical cancer models." (PMID 29891791, 2018). "The mRNA levels of IL4 and IL10 in tumor cells separated from different xenografts were detected." (PMID 29368606, 2018). "In the tumor microenvironments, there are not only IFN-γ, TNF-a, and GM-CSF which could activate macrophages like M1 macrophages, but also IL-4, IL-10 and CSF-1 which induce M2 macrophages differentiation." (PMID 30180849, 2018). "In a first phase (elimination phase), the stimulated immune system produced many costimulating cytokines (TNFα, IL1, IFNα, TLR, ICAM1, IL2, IL12, IFNγ,) and less inhibitors (IL10, IL4, IL13, PD1/PD-L1, prostaglandins, LAG-3, TGFβ) resulting in efficient tumor cell killing." (PMID 29492219, 2018). "Administering anti-IL-10 monotherapy biweekly or in combination with cell-based treatments did not lead to a decrease in tumor size because IL-4 plays a role that is similar to that of IL-10." (PMID 35847834, 2018). "Moreover, metformin-treatment lowered expression of IL4, IL10 and IL13 in tumour cells and inhibited metastasis formation and angiogenesis in a mouse model of LLC, a xenograft model of breast and prostate cancer." (PMID 30577495, 2018). "In this work, we focused on increasing the M1-to-M2 macrophage and the Th1-to-Th2 helper cell ratios by injecting anti-tumor polarized cells (M1 macrophages and Th1 helper cells) and by disrupting pro-tumor positive feedback loops driven by TGF-β, IL-4 and IL-10." (PMID 35847834, 2018). "Only the cytokines GM-CSF, IFN-γ, IL-2, IL-4 and TNF-α were detected at relevant concentrations in the presence of UniCAR CD28/ζ-armed T cells, tumor cells and TM substantiating that cytokine secretion occurs in a strictly TM- dependent- and target-specific manner." (PMID 29484126, 2018). "Analysis of the humoral immune response to vaccination showed that most patients with no detectable tumor (adjuvant treatment) had low IL-4 and IL-10 initial values." (PMID 29849947, 2018). "Importantly, the GLPS and triterpene acid were demonstrated to promote the production of cytokines, such as IL-1β, IL-4, IL-6, IL-12, IL-17, RANTES, TNF-α and IFN-γ, and thus to exhibit immuno-modulation and anti-tumor activities." (PMID 30139984, 2018). "Although all six types of macrophages showed increased phagocytosis of tumor cells in the presence of TTI-621, M(-), M(IL-4) and M(HAGG+IL-1β) macrophages exhibited slightly lower phagocytic capabilities compared to the M(IFN-γ), M(IFN-γ + LPS) and M(IL-10 + TGFβ) subsets." (PMID 29084248, 2017). "Regarding this tumour entity, the interaction between malignant cells and TAMs occurs through the plasminogen activator urokinase (uPA) and its specific receptor uPAR, mainly through the activation of ERK1/2 and increase in the production of IL-4." (PMID 28381274, 2017). "In this study, we noticed that anti-IL-25 treatment only reduced the IL-4-producing Th2 cells in the tumor microenvironment, but did not affect the expression of IL-5 and IL-13." (PMID 27909985, 2017). "Once embedded in the tumour microenvironment, the monocytes mature into the predominant M2 expressing CD163 (haemoglobin scavenger receptor) macrophages and are activated by Th 2 cytokines interleukin-4 (IL-4) and IL-10." (PMID 28913366, 2017).
tumor (continued). "More specifically, tumor-specific T cell response to tumor-associated antigens MAGE-6 and EphA2 is characterized by a predominance of T cells synthesizing IL5 and IL4, together with reduced levels or a complete absence of T lymphocytes expressing IFNγ." (PMID 28409322, 2017). "Within the tumor microenvironment, TAMs are forced forwards M2 phenotypes by GBM cells via secreting a wide variety of factors such as IL10, IL4, IL6, M-CSF, macrophage inhibitory factor (MIF), TGFβ, and prostaglandin E2 (PGE2), and subsequently support tumor growth and invasion." (PMID 29132376, 2017). "Significant activation of DNA binding activity of STAT6, phosphorylation of STAT6 as well as IL-4, IL-4Rα and p21 expression were found in the tumor tissues of IL-4 mice compared to non-transgenic mice." (PMID 26993600, 2016). "Treatment of ascophyllan led to substantial increases in the proportions of IFN-γ- and TNF-α-producing CD4 and CD8 T cells in the spleen and tumor drLN, whereas IL-4- or IL-17-producing CD4 and CD8 T cells were not increased by ascophyllan treatment." (PMID 27008707, 2016). "Immunohistochemistry showed that IR-induced IL-4 increased the expression of major components related to p-Stat6, mesenchymal trait marker, Vimentin; invasiveness marker, MMP-9; stemness maintenance marker, Sox2; and tumor proliferation marker, Ki-67." (PMID 27895317, 2016). "Spleen cells from mock-vaccinated mice were not significantly stimulated to produce increased levels of IL-4 when cultured in tumor-conditioned medium." (PMID 27598146, 2016). "Several environmental factors, including interleukin-4 (IL-4), tumor-derived transforming growth factor-β (TGFβ), and macrophage migration inhibitory factor (MIF), create a permissive tumor microenvironment for metastasis (TMEM) where the cancer cells intravasate." (PMID 27006653, 2016). "This and the fact that CD137L-DCs have been shown to stimulate proliferation, IFN-γ secretion and the cytolytic activity of T cells more potently than GM-CSF and IL-4 derived DCs14, 15, 16, advocate the evaluation of CD137L-DCs as vaccines in human tumour immunotherapy." (PMID 27431276, 2016). "Interestingly, IL-4 treated, M2-like BMDM mediated anti-GD2 mAb mediated killing of Vorinostat pre-treated tumor cells even at low effector : target ratio's (right)." (PMID 27471639, 2016). "Notably, both of the representative Th2 cytokine genes Il4 and Il13 and the representative Th1 cytokine gene Ifng were significantly upregulated in NM11-shsST2 tumours." (PMID 27882929, 2016). "Expression of IDO in the tumor microenvironment inhibits NK function by downregulation of activating NK receptors DNAM-1, NKp30, NKp44, and NKG2D, inhibition of IFN-γ production, increased IL-4 and IL-13 secretion, and induction of NK cell apoptosis." (PMID 27148255, 2016). "Expression of p21 was also increased in the tumor of IL-4 mice compared with those of non-transgenic mice." (PMID 26993600, 2016). "In this process, dendritic cells (DCs) maturation can be suppressed by changes in the cytokine balance (increased VEGF, TGFβ, IL-10, IL-6, and COX-2 and reduced IL-4, IL-12, IFN-α, and IFN-γ) within the tumor, which significantly impairs the antigen presenting function of these cells." (PMID 28053982, 2016). "50% (7 out of 14) of the tumour samples showing a high level of expression before NAC were altered to a low/negative level of expression of IL-4 after NAC." (PMID 27777963, 2016). "Moreover, some studies found that macrophage treated with IL-4 or IL-13 (alternatively activated macrophage) could express high levels of dectin-121, suggesting that these immune regulatory cytokines might also influence tumor cell dectin-1 expression, like a tumor-host cytokine interaction." (PMID 27600310, 2016). "In our study, we observed a high level of proinflammatory cytokines, such as TNF-α, IFN-γ and IL-12 in sera from SZU-101-treated tumour-bearing mice, while no induction of TH-2 cytokines IL-4, IL-5 or IL-10 was detected." (PMID 25887995, 2015).
tumor (continued). "Our experiments demonstrated that ATRA, IL-4 or LPS failed to induce in vitro differentiation of isolated Ly6C+ MDSCs, nor did they enhance the anti-tumor effects of DC vaccine (unpublished results)." (PMID 26181041, 2015). "Although not significant, a tendency to increase in the concentration of IL-4 was verified on the 13th day of development of the EAT, which could be reflecting a Th2 immune response against the tumor." (PMID 26347589, 2015). "The results of the present study clearly show that IL-15 DCs, but not conventional IL-4 DCs, can induce an activated phenotype in NK cells and enhance NK cell cytotoxicity against both NK-sensitive as well as NK-insensitive tumor cells." (PMID 25951230, 2015). "Infusion of autologous infiltrating lymphocytes depleting CD4+CD25+ regulatory T cells to BC murine, was capable of increasing activation and proliferation of CD4+ and CD8+ T cells, enhancing IL-4 and IFN-γ secretion, postponing tumor growth and prolonging survival." (PMID 26462021, 2015). "While these preclinical studies documented significant reduction in tumor growth at the injection sites of IL-4 expressing tumor cells, the effect of IL-4 on the metastatic spread of these tumors was not assessed." (PMID 27563494, 2015). "Characterization of cytokine expression patterns in these accumulated myeloid splenocytes in tumor bearing mice revealed a Th2 dominant pattern with decreased IL-2, IL-12, interferon (IFN)-γ and tumor necrosis factor (TNF)-α and elevated IL-4 and transforming growth factor (TGF)-β." (PMID 26690220, 2015). "Freshly isolated monocytes were differentiated into MDM with M-CSF before polarization into M1 using IFN-γ and LPS or into M2 macrophages by IL-4 and IL-13, or were co-cultured with NCI-H460 or MCF-7 tumour cells to better mimic a realistic situation of macrophage polarization by tumours." (PMID 25902944, 2015). "The lack of a significant percentage of IL-4 and IL-17 producing γδ T cells and the absence of a survival advantage in tumor-bearing TCRδ-/- mice appears to indicate that γδ T cells in this model do not have a significant immunoregulatory role." (PMID 25955158, 2015). "Examining both the cytokine profile and tumor protection capacity within a panel of type I NKT agonists, there was a strong correlation between the Th1 profile (in terms of IFN-γ:IL-4 ratio or IFN-γ production) and magnitude of protection in the mice from tumor growth in CT26 lung metastasis model." (PMID 25389427, 2014). "Within the tumor microenvironment, in the absence of Rip2, we found a cytokine signature enriched in IL-4 and G-CSF, polarizing towards a M2 phenotype as reflected in increased production of IL-10 and arginase-1." (PMID 24733360, 2014). "Macrophages are known to produce CCL2 in response to IL-4/IL-13 stimulation, and the increase in CCL2 production we detected during lung tumorigenesis indicates that there is a Th2 response occurring in lungs during tumor formation." (PMID 25505466, 2014). "Many epithelial cancers express receptors for type 2 mediators such as IL-4 and IL-13, allowing for a direct effect on tumor growth, death, and proliferation that is independent of their effect on immunocytes." (PMID 25101088, 2014). "By suppressing interferon-gamma expression and release from antigen-specific T cells, and locally enhanced IL-4 and IDO levels COX-2 may contribute to a tumor-permissive milieu." (PMID 25501829, 2014). "The higher proliferation of M-406 cells observed when cultured with CMO from both Naïve CBi/L and CBi mice indicates that these media would contain factor/s like IL-2, IL-4, INF-γ, IL-10, TNF-α and many others, yet to be identified, capable to stimulate or inhibit tumor growth." (PMID 24885995, 2014). "IL-4 levels in the tumor/non-trained group increased relative to the control group (P=0.0552) and were significantly greater than the levels observed for the no tumor/trained group (P=0.0275)." (PMID 24520305, 2014).
tumor (continued). "In addition, IL-4 also disturbs anti-tumor immunity by down-regulating the expression of Th1 cytokines and impairing the CD8+ T cell immune response in the tumor microenvironment." (PMID 25484626, 2014). "As already proposed by and confirmed in this study combined IL-4 and TNFα treatment exerts a synergistic effect on the increase of HLA class I antigen expression in RCC cells, which might enhance T cell-based anti-tumor responses." (PMID 24885059, 2014). "The synergetic effect on the enhancement of anti-tumor immune response among alum, PS and HH2 might be attributed to the following aspects: alum vaccination resulted in an increase in IL-4-producing cells to promote Th2-type immune responses." (PMID 25070035, 2014). "Of these genes, IL-4 and CXCL10 were newly identified DEGs that may contributed to tumor suppression." (PMID 25108500, 2014). "Two M2 cytokines (IL-10 and TGF-β) were marginally greater in the tumor/non-trained group than in the tumor/trained group and one cytokine (IL-4) was marginally greater in the tumor/trained group than in the tumor/non-trained group." (PMID 24520305, 2014). "Upon activation, human peripheral Vγ9Vδ2 T cells also can express IL-4, IL-10, and TGF-β and inhibit T cell proliferation, thus developing a regulatory profile that may play a role in the suppression of anti-tumor responses." (PMID 25538706, 2014). "GNP10 also enhanced the ability of HEp-2-treated DCs to stimulate the production of IL-4 by CD3+T cells, suggesting that HEp-2/GNP10-treated DCs could have an impaired anti-tumor activity." (PMID 24802102, 2014). "Most likely, this process is also modulated by IL-4, which polarizes macrophages towards promoting the invasiveness and spread of the tumor; these functions are blocked in the lack of IL-4." (PMID 23576856, 2013). "Considering that IL-4/IL-13 and IFN-γ/IL-12 counter regulate each other, our finding that IL-13 is protective is in line with the previous observation that IFN-γ and IL-12 can be tumor-promoting in DMBA/TPA carcinogenesis." (PMID 24403255, 2013). "In contrast, GM-CSF+IL-4 conditioning leads to predominant migration of CD1a+ LC and DDC subsets in a sustained mature state that predominantly release IL-12p70 and can induce both Th1 and tumor-specific CD8+ high-avidity effector T cells." (PMID 23875023, 2013). "Increased tumor infiltrating immune cells, including CD4+ and CD8+ T cells, NK cells, and macrophages were documented following administration of oHSVs encoding IL-4 and IL-12 as compared to non-cytokine encoding oHSVs." (PMID 24312353, 2013). "The immune cells from pulchellin-treated mice also produced statistically higher concentrations of TNF-α by PEC cells, and IL-4, IFN-γ and IL-10 by splenocytes, and lower concentrations of IL-6 (PEC cells) and TGF-β (splenocytes), than the cells from tumor control mice." (PMID 22827934, 2012). "Although IL-4, IFNγ, and several other tumor-derived cytokines and growth factors modulate macrophage phenotypes in vitro and in vivo, the molecular mechanisms that promote M1 or M2 TAM subsets within the tumor microenvironment are incompletely understood." (PMID 22938502, 2012). "However, administration of alpha-GalCer to tumor bearing mice enhances the ability of iNKT cells to suppress, despite the fact that alpha-GalCer induces strong expression of both IFN-gamma and IL-4 from iNKT cells." (PMID 22880059, 2012). "This together with our observation that macrophages underwent M2 polarization in week three even in the absence of IL-4 further supports our finding that the presence of M2 polarized macrophages enhance tumor cell invasion." (PMID 22792213, 2012). "Histological analysis of murine OTCs in week three had shown that macrophage containing cultures cultivated in absence of IL-4 showed enhanced areas of tumor cells protruding into the dermal equivalent." (PMID 22792213, 2012).
tumor (continued). "In relation to their ‘tunable’ function, mast cells in the local environment can also be detrimental for the tumours themselves, secreting immune mediators such as IL-1, IL-4, IL-5, IL-6 and TNF-α that can induce apoptosis of tumor cells and recruit inflammatory cells." (PMID 24212964, 2011). "IL-4, the signature cytokine of a TH-2 type immune response, is a major activator of the TAM phenotype in the tumor microenvironment, and the effects of IL-4 collectively prime TAM with the ability to promote tumor growth, invasion and metastasis." (PMID 21939504, 2011). "Neutralization of IL4 significantly enhanced the effectiveness of TRAIL in epithelial tumors, confirming that factors derived from the tumor microenvironment can diminish the response of tumor cells to TRAIL." (PMID 20661477, 2010). "Although tumor necrosis was not confirmed by biological examination, IL4-PE induced change in gadolinium enhancement representing positive tumor necrosis was confirmed by histological examination of tissues in several patients." (PMID 22069569, 2010). "According to our work, Th1 cytokines (IL-2 and IFN-γ) and Th2 cytokines (such as IL-4 and IL-5) are not the major cytokines produced by tumours." (PMID 17261184, 2007). "This translated into a cytolytic activity against K562 cells with a median specific lysis of 26% at high effector cell numbers as determined by propidium iodide uptake, whereas IL-4/TNF-DC did not induce any tumor cell lysis (p = 0.006)." (PMID 17894866, 2007). "CD8+ Tc cells that are induced in a primary MLTC do not produce IFN-γ, and the tumor-specific Tc response is enhanced by IL-4 but suppressed by IFN-γ or IL-12." (PMID 9814607, 1998). "The generated CD4+ T cells secreted interferon (IFN)-gamma, tumour necrosis factor (TNF)-alpha, TNF-beta, and interleukin (IL)-6 (but not IL-4), and exhibited a high level of cytolytic activity against several tumour cell lines." (PMID 8554971, 1996). "We have already demonstrated that interleukin 4 (IL-4) augments proliferation of tumour-infiltrating lymphocytes (TILs) without altering the cytotoxic activity against autologous tumour cells." (PMID 8855979, 1996). "Unlike IL-4/IL-13 polarized macrophages, xenoline-polarized TAMs exhibit a broader spectrum of transcriptional and functional states that more closely mirror the complexity of the tumor microenvironment." (PMID 40386422, 2025). "Additionally, it was recently reported that IL-4 controls monocyte and macrophage immunosuppression in NSCLC, and that the relevant site of IL-4 signaling is not the tumor itself, but the bone marrow, where it drives pro tumorigenic myelopoiesis." (PMID 40534853, 2025). "However, the most commonly used clinical strategy still relies on inducing DCs in vitro using granulocyte-macrophage colony-stimulating factor (GM-CSF) and interleukin-4 (IL - 4) (GM/IL4-DCs), which often results in a heterogeneous cell population with suboptimal anti-tumor function." (PMID 40977690, 2025). "When FL/GM-DCs loaded with B16-OVA tumor lysates were co-cultured with CD4+T cells that had been isolated from OT-II mice, we detected a significant increase in the activation and proliferation of CD44+CD4+T cells relative to those co-cultured with GM/IL4-DCs (37% vs. 25.5%)." (PMID 40977690, 2025). "In addition, our studies have revealed that the triple combination therapy is capable of offering improved antitumor efficacy in the TC-1 tumor mouse model, which is related to an increase in antigen-specific lymphocyte proliferation, CD8 + cytotoxicity, and IFN-γ, IL-4, and IL-10 induction." (PMID 40403026, 2025). "To see whether similar results are found in M1 macrophages polarized by stimuli other than IFNγ + LPS and M2 macrophages by IL-4 or TGF-β1, we stimulated the macrophages with a tumor conditioned media of 2D- (2D TCM) or 3D-cultured tumor cells (3D TCM), IFNγ alone, TNFα, IL-4 or TGF-β1." (PMID 40050422, 2025).